FABP4 (fatty acid binding protein 4)
Description:
Lipid transport protein in adipocytes. Binds both long chain fatty acids and retinoic acid. Delivers long-chain fatty acids and retinoic acid to their cognate receptors in the nucleus.
Synonyms: ALBP; A-FABP; AFABP; aP2; HEL-S-104
Tractability: Small molecule: a structure with a bound ligand is known; a high-quality ligand is known; it has a high-quality binding pocket; it belongs to a druggable protein family. PROTAC: a small molecule that binds it is known.
Target class: Fatty acid binding protein family; Auxiliary transport protein
Gene: Protein-coding gene on chromosome 8 (81,477,651 to 81,483,239, reverse strand). Ensembl gene ENSG00000170323.
Subcellular location: Cytoplasm; Nucleus
Subcellular location (Human Protein Atlas): Cytosol; Nucleoplasm
Pathways (Reactome):
Developmental Biology: Transcriptional regulation of white adipocyte differentiation
Gene expression (Transcription): MLL4 and MLL3 complexes regulate expression of PPARG target genes in adipogenesis and hepatic steatosis
Metabolism: Triglyceride catabolism
Gene Ontology:
Molecular function: fatty acid binding; lipid transporter activity; long-chain fatty acid binding; long-chain fatty acid transmembrane transporter activity; hormone receptor binding; lipase activator activity; lipid binding
Biological process: fatty acid transport; long-chain fatty acid transport; positive regulation of cold-induced thermogenesis; triglyceride catabolic process; white fat cell proliferation
Cellular component: extracellular exosome; cytoplasm; cytosol; lipid droplet; nucleus
Genetic constraint (gnomAD): Loss-of-function variants: 13 observed, 9.88 expected, observed/expected ratio (o/e) 1.32, 90% interval 0.85 to 1.87. That is too few expected variants to judge how well the gene tolerates losing a copy. Missense variants: 122 observed, 130.08 expected, observed/expected ratio (o/e) 0.94, 90% interval 0.81 to 1.09. Synonymous variants: 45 observed, 47.33 expected, observed/expected ratio (o/e) 0.95, 90% interval 0.75 to 1.22.
Homologues: Orthologues: chimpanzee FABP4 (100% identical), macaque FABP4 (98% identical), dog FABP4 (95% identical), mouse Fabp4 (92% identical), pig FABP4 (89% identical), guinea pig FABP4 (86% identical), rat Fabp4 (78% identical), tropical clawed frog pmp2 (53% identical), tropical clawed frog fabp4 (52% identical), Caenorhabditis elegans lbp-9 (48% identical), Drosophila melanogaster fabp (43% identical), zebrafish rbp7a (40% identical), and 1 more. Paralogues in human: PMP2 (67% identical), FABP3 (64% identical), FABP9 (64% identical), FABP7 (57% identical), FABP12 (55% identical), FABP5 (52% identical), RBP2 (40% identical), RBP7 (39% identical), CRABP1 (36% identical), RBP1 (36% identical), CRABP2 (34% identical), FABP2 (30% identical), and 3 more.
Diseases named in the same sentence as FABP4 in open-access papers:
FABP4 is named in the same sentence as 335 diseases in open-access papers, as found by Europe PMC text mining. Sharing a sentence is not in itself a finding about the gene and the disease. The quoted sentences say what the papers report.
Obesity (346 papers, 2007 to 2026). Accumulation of substantial excess body fat. "This review critically summarizes recent preclinical evidence on natural bioactive compounds that regulate FABP4 expression and associated adipogenic programs in models of adipogenesis and diet-induced obesity." (PMID 41683732, 2026). "Recent studies demonstrate that adipose FABP4 promotes obesity-associated breast cancer development, thus suggesting FABP4 as a novel player linking obesity and breast cancer risk." (PMID 40870889, 2025). "Elevated serum FABP4 concentrations are associated with obesity, insulin resistance, hypertension, inflammation, atherosclerosis, and metabolic syndrome, thus positioning FABP4 as a potential independent biomarker for metabolic and cardiovascular diseases." (PMID 41187309, 2025). "FABP4 has also been implicated in metabolic regulation, potentially linking obesity to breast cancer risk." (PMID 40485730, 2025). "Elevated levels of FABP4 have been associated with liver steatosis, particularly in individuals with metabolic conditions like diabetes and obesity." (PMID 40868056, 2025). "FABP4 is highly expressed in obesity-associated pancreatic cancer, promoting tumor progression and immunosuppression." (PMID 40717587, 2025). "Given the established link between obesity-associated lipid dysregulation increased breast cancer risk, FABP4 and FABP5 play critical roles in facilitating fatty acid oxidation and metabolism, as well as promoting oncogenic lipid signaling pathways." (PMID 40106183, 2025). "Conversely, FABP4 is markedly upregulated in obesity-associated HCC, particularly in response to high-fat diets and fatty acid exposure." (PMID 41149452, 2025). "For example, FABP4 upregulates ANGPTL4 in obesity-associated triple-negative breast cancer, promoting angiogenesis and chemoresistance." (PMID 40717587, 2025). "FABP4 has also been associated with obesity and metabolic diseases, and is considered a promising therapeutic target for type 2 diabetes and atherosclerosis due to its roles in regulating metabolic and inflammatory pathways." (PMID 41226657, 2025). "Circulating FABP4 promoted obesity-associated breast cancer by increasing mammary tumor stemness and aggressiveness through the IL-6/STAT3/ALDH1 axis." (PMID 41392988, 2025). "FABP4 levels are elevated in obesity and cancer, and mutations in the gene have been identified in cases of primary lymphedema." (PMID 40759794, 2025). "This study aims to investigate the association between FABP4 levels, diabetes mellitus, and obesity within various ethnic groups." (PMID 38731797, 2024). "In this study, significant positive associations were found between the plasma level of FABP4 and obesity markers: BMI (r = 0.496, p < 0.001), hip circumference (r = 0.463, p < 0.001), and waist circumference (WC) (r = 0.436, p < 0.001)." (PMID 38731797, 2024). "In line with earlier studies showing that circulating FABP4 is closely associated with obesity and metabolic syndrome, this finding highlights the significant role of macrophage in releasing FABP4 among the BMI-selected cohort." (PMID 39028355, 2024). "In exploring obesity/breast cancer risk, we have identified adipose fatty-acid binding protein (A-FABP, also known as FABP4, aP2) as a new molecular mechanism linking obesity-associated breast cancer development." (PMID 39054536, 2024). "It is well established that FABP4-deficient mice are protected against obesity-induced hyperinsulinemia, insulin resistance, and glucose intolerance." (PMID 37279064, 2023). "It is well established that circulating serum FABP4 is positively associated with body mass index and exerts hormonal regulations in obesity-associated diseases." (PMID 36418670, 2023). "Total genetic deletion of Fabp4 in mice confers protection against obesity-associated insulin resistance, glucose intolerance, inflammation, atherosclerosis, and certain cancers." (PMID 37279064, 2023).
Obesity (continued). "Under conditions of obesity, loss of insulin sensitivity in adipocytes results in unsuppressed lipolysis, which leads to increased levels of hormonal FABP4." (PMID 37172691, 2023). "Circulating FABP4 levels are widely associated with obesity risk factors such as triglyceride, cholesterol, and leptin levels in humans and rodents." (PMID 37628833, 2023). "Higher FABP4 has been linked to metabolic diseases such as obesity and diabetes and higher FABP3 in the plasma has been linked to fatigue, physical activity intolerance, and muscle atrophy." (PMID 37697678, 2023). "FABP4 has been identified as a potential biomarker for atherosclerosis and is strongly associated with inflammation, obesity, diabetes, and cardiovascular disease." (PMID 38203557, 2023). "In humans, elevated FABP-4 concentrations have been associated with obesity, insulin resistance, atherosclerosis, type 2 diabetes, and metabolic syndrome." (PMID 37833736, 2023). "This aberrant FABP4 secretion stimulates glucose production from the liver, impairs beta-cell function, and potentiates the metabolic abnormalities associated with obesity." (PMID 37172691, 2023). "As an adipose-derived hormone, FABP4 is primarily expressed in adipocytes as a cellular marker of adipocyte maturation and is mainly involved in immunometabolism implications and obesity-associated tumors." (PMID 37628833, 2023). "Since Fabp4–/– mice are also protected against obesity-associated hyperinsulinemia, the decrease in lipolysis-driven insulin secretion has been considered as one potential contributing factor to their reduced hyperinsulinemia and improved metabolic health." (PMID 37279064, 2023). "Because FABP4 negatively regulates PPARG at the posttranscriptional level and represses preadipocyte differentiation, lower expression of FABP4 has been associated with obesity in different studies." (PMID 37255997, 2023). "Taken together, these results suggest a role for WAT in modulating lipid profiles and emphasize the association between FABP4 expression and TG levels in a population with severe obesity." (PMID 36769659, 2023). "Levels of circulating fatty acid binding protein 4 (FABP4) protein are strongly associated with obesity and metabolic disease in both mice and humans, and secretion is stimulated by β-adrenergic stimulation both in vivo and in vitro." (PMID 37172691, 2023). "FABP4 is associated with obesity, insulin resistance, diabetes mellitus, hypertension, cardiac dysfunction, atherosclerosis, and cardiovascular events." (PMID 36611783, 2023). "Growing studies demonstrate that elevated circulating FABP4 levels correlate with an increased risk for obesity, type 2 diabetes, various cardiovascular diseases, and cancers in a wide variety of populations." (PMID 37628833, 2023). "Fatty-acid binding protein 4 (FABP4) gene polymorphisms led to increased morning FABP4 levels in children (ages 2–12 years) with obesity and OSA." (PMID 37296808, 2023). "It has been increasingly recognized that FABP4 dysfunction is associated with various metabolic syndromes, including obesity, diabetes, cardiovascular diseases, and metabolic inflammation." (PMID 37628833, 2023). "An increase in circulating FABP4 levels has been associated with hypertension, diabetes mellitus, insulin resistance, obesity, atherosclerosis, cardiovascular events and cardiac dysfunction." (PMID 37255976, 2023). "Breast cancer patients display higher blood concentration of FABP4, implying elevated levels of circulating FABP4 as a specific promoter of the obesity-associated breast cancer." (PMID 35899119, 2022). "Collectively, FABP4 coordinates fatty acid metabolism and DNA methylation to modulate the development of obesity-associated cancer." (PMID 35899119, 2022). "Fatty acid-binding protein 4 (FABP4) is a regulator of lipid metabolism and is associated with obesity, insulin resistance, and type 2 diabetes." (PMID 35647197, 2022).
Obesity (continued). "FABP4 was also previously linked to the invasion and migration of colon cancer cells and obesity-associated breast cancer development." (PMID 36230586, 2022). "Collectively, circulating FABP4 opens new diagnosis and therapy perspectives for breast cancer, especially for obesity-associated breast cancer." (PMID 35899119, 2022). "For example, FABP4 promotes tumour cell progression via the IL-6/STAT3/ALDH1 axis in obesity-associated breast cancer." (PMID 35198079, 2022). "FABP4 promotes the occurrence of obesity-related breast cancer and is a novel role in linking obesity and breast cancer risk." (PMID 36532833, 2022). "Several molecular and cellular events have been proposed to mediate this central role of FABP4 in the regulation of metabolism in obesity and to link breast cancer risk to obesity." (PMID 36060264, 2022). "Previous evidence displayed that FABP4 mediated lipid-associated metabolism in obesity, type 2 diabetes mellitus, schizophrenia and cognition." (PMID 36670935, 2022). "Omentin-1 and fatty acid-binding protein 4 (FABP4) are adipose tissue adipokines linked to obesity-associated cardiovascular complications." (PMID 34609443, 2021). "FABP4 regulates hepatic production of glucose, and the mice with FABP4 deficiency have a lower risk for obesity-induced insulin resistance and type 2 DM." (PMID 34880765, 2021). "Previous studies have established that FABP-4 is associated with type 2 DM, gestational DM, cardiovascular diseases, obesity, and metabolic syndrome." (PMID 34217172, 2021). "Recently, FABP4, a member of a family of circulating adipose fatty acid binding proteins, has emerged as a new link in the obesity-associated breast/mammary tumor development." (PMID 33801973, 2021). "In individuals with obesity, the adipokine FABP4 is upregulated in the adipose tissue and is linked to obesity-related breast cancer." (PMID 34944905, 2021). "In a previous PEA‐proteomics study, ADM and FABP4 were positively associated with BMI‐defined obesity." (PMID 34151535, 2021). "Studies also showed positive associations between serum FABP4 and other cardiovascular risk factors like obesity, dyslipidemia, and insulin resistance." (PMID 34789046, 2021). "Various studies showed that FABP4-deficient mice gained more weight upon induction of dietary obesity." (PMID 31562532, 2020). "Fatty acid-binding protein 4 (FABP4) acts as a novel adipokine, and elevated FABP4 concentration is associated with obesity, insulin resistance and atherosclerosis." (PMID 32539832, 2020). "GPX activity directly correlated with HDL-C in obesity plus one component of MetS and were inversely associated with FABP4 in obese patients." (PMID 32344656, 2020). "In obese breast-cancer patients, in which adipokines such as leptin and resistin known to be related to obesity and that increase mammary tumor risk, an elevation of FABP4 correlated with tumor size and stage, and with lymph node invasion was found." (PMID 32856199, 2020). "Downregulated genes included FABP4, a fatty acid-binding protein associated with activation of proinflammatory macrophages in breast cancer, obesity and leukemia progression." (PMID 33276795, 2020). "Elevated serum concentration of FABP4 is associated with obesity, insulin resistance, hypertension, dyslipidemia, atherosclerosis, renal dysfunction, purine metabolism, heart failure and cardiovascular events." (PMID 32539832, 2020). "Mice deficient in FABP4 are resistant against metabolic abnormalities associated with obesity, including diabetes and atherosclerosis." (PMID 32856199, 2020). "Several studies have demonstrated that FABP4 is associated with obesity, as well as insulin resistance and metabolic syndrome." (PMID 32887447, 2020). "Further, miR-148a and miR-21 are also known to promote expression of FABP4, an obesity-associated gene, by promoter hypomethylation, leading to metabolic aberrations and eventually obesity." (PMID 32414045, 2020).
Obesity (continued). "Reduced lipolysis efficiency was observed in adipocyte-specific-FABP4-deficient mice, and these mice were also found with ameliorated insulin resistance during diet-induced obesity." (PMID 33105856, 2020). "It has been reported that increased circulating FABP4 levels are associated with obesity, insulin resistance, T2DM, cardiovascular disorders, arterial hypertension, cardiac dysfunction, kidney damage, fatty liver disease, and atherosclerosis." (PMID 30857223, 2019). "Other studies have described an association between FABP4 and obesity markers, such as BMI and fat mass, as well as obesity-related diseases, including polycystic ovary syndrome." (PMID 30818771, 2019). "Deletion of the FABP4 gene protected mice against insulin resistance as well as hyperinsulinemia associated with both diet-induced obesity and genetic obesity." (PMID 30857223, 2019). "Reduction of FABP4 levels has been associated with a better response to insulin and protective effect against obesity." (PMID 28382233, 2017). "FABP4 is secreted from adipocytes and macrophages and has recently been investigated as a marker that is closely associated with obesity and metabolic syndrome." (PMID 28654680, 2017). "Elevated serum levels of FABP4 were associated with obesity, insulin resistance, dyslipidemia and hypertension in healthy people." (PMID 28654680, 2017). "Clinical and experimental studies indicate an important role of lipocalin-2, FABP4, and leptin as inflammatory adipokines associated with obesity and related complications." (PMID 28757686, 2017). "Increased expression of FABP4 in plasma and PBMCs has been associated with obesity and atherogenic dyslipidemia." (PMID 28933365, 2017). "Elevated levels of FABP4 are closely linked with the development of obesity, IR, DM, hypertension, CAD and atherosclerosis." (PMID 27864793, 2017). "Because circulating levels of FABP4 are associated with obesity and metabolic diseases, we investigated the relationship between HFD, PrSC activation and PCa progression in an in vivo model." (PMID 29340091, 2017). "It has also been reported that elevated serum FABP4 concentration is associated with obesity, insulin resistance, type 2 diabetes mellitus, hypertension, cardiac dysfunction, renal dysfunction, dyslipidemia, atherosclerosis and cardiovascular events." (PMID 27124282, 2016). "Amongst the other differentially expressed FABPs, FABP4 was released from adipocytes, implicated in obesity and its possible involvement in the malignant progression of prostate cancer has been investigated previously." (PMID 27779102, 2016). "It has also been shown that an elevated serum level of FABP4 is associated with obesity, insulin resistance, hypertension, cardiac dysfunction, atherosclerosis and cardiovascular events." (PMID 26754658, 2016). "Sufficient evidence has confirmed that the plasma biomarker FABP4 is closely associated with obesity and metabolic syndrome." (PMID 26752184, 2016). "The inhibition of FABP4 can improve type 2 diabetes mellitus and atherosclerosis in mouse model, and elevated circulating FABP4 levels are associated with obesity, metabolic disease, and cardiac dysfunction in humans." (PMID 27819006, 2016). "Recent studies have confirmed that FABP4 levels were positively associated with metabolic risk factors, such as obesity, insulin resistance, dyslipidemia and the heart failure marker NT-pro BNP." (PMID 26752184, 2016). "Increased circulating FABP4 level is associated with obesity, insulin resistance and atherosclerosis." (PMID 26754658, 2016). "Elevated serum levels of FABP4 were associated with obesity, insulin resistance, dyslipidemia and hypertension in healthy subjects." (PMID 26752184, 2016). "Adipocyte fatty acid binding protein (FABP4) has been recently characterized as an adipokine that is closely associated with obesity and metabolic syndrome." (PMID 26752184, 2016).